CACNG2 (calcium voltage-gated channel auxiliary subunit gamma 2)
Description:
Regulates the trafficking and gating properties of AMPA-selective glutamate receptors (AMPARs). Promotes their targeting to the cell membrane and synapses and modulates their gating properties by slowing their rates of activation, deactivation and desensitization. Does not show subunit-specific AMPA receptor regulation and regulates all AMPAR subunits. Thought to stabilize the calcium channel in an inactivated (closed) state.
Synonyms: stargazin; MGC138502; MGC138504; MRD10
Tractability: Small molecule: an approved drug acts on it; a structure with a bound ligand is known; a high-quality ligand is known; it belongs to a druggable protein family. Antibody: its Gene Ontology location is reachable by antibodies, with high confidence; UniProt predicts a signal peptide or a membrane-spanning region. PROTAC: a small molecule that binds it is known.
Gene: Protein-coding gene on chromosome 22 (36,560,857 to 36,703,752, reverse strand). Ensembl gene ENSG00000166862.
Subcellular location: Membrane; Synapse, synaptosome
Pathways (Reactome):
Neuronal System: Presynaptic depolarization and calcium channel opening; Trafficking of AMPA receptors
Developmental Biology: LGI-ADAM interactions
Gene Ontology:
Molecular function: protein binding; channel regulator activity; voltage-gated calcium channel activity; ionotropic glutamate receptor binding
Biological process: positive regulation of synaptic transmission, glutamatergic; postsynaptic neurotransmitter receptor diffusion trapping; regulation of AMPA receptor activity; transmission of nerve impulse; calcium ion transmembrane transport; calcium ion transport; eye blink reflex; neurotransmitter receptor localization to postsynaptic specialization membrane; positive regulation of protein localization to basolateral plasma membrane; protein targeting to membrane; regulation of postsynaptic membrane neurotransmitter receptor levels; response to calcium ion
Cellular component: AMPA glutamate receptor complex; endocytic vesicle membrane; plasma membrane; postsynaptic density membrane; voltage-gated calcium channel complex; cell surface; cerebellar mossy fiber; glutamatergic synapse; hippocampal mossy fiber to CA3 synapse; membrane; organelle; Schaffer collateral - CA1 synapse; somatodendritic compartment; synapse
Genetic constraint (gnomAD): Loss-of-function variants: 2 observed, 23.25 expected, observed/expected ratio (o/e) 0.086, 90% interval 0.034 to 0.27. The upper end of that interval is the gene's LOEUF score, 0.27, which puts it in group 1 of 6, group 1 being the genes least tolerant of losing a copy. Missense variants: 339 observed, 456.81 expected, observed/expected ratio (o/e) 0.74, 90% interval 0.68 to 0.81. Synonymous variants: 167 observed, 184.19 expected, observed/expected ratio (o/e) 0.91, 90% interval 0.8 to 1.03.
Gene-disease validity (ClinGen):
ClinGen rates the evidence that CACNG2 causes each of these diseases.
complex neurodevelopmental disorder (autosomal dominant): Limited. A disorder that involves more than one phenotype associated with the central nervous system, including but not limited to intellectual disability, autism, and seizures (epilepsy).
Homologues: Orthologues: chimpanzee CACNG2 (100% identical), dog CACNG2 (100% identical), guinea pig CACNG2 (100% identical), macaque CACNG2 (100% identical), pig CACNG2 (99% identical), mouse Cacng2 (99% identical), rat Cacng2 (99% identical), tropical clawed frog cacng2 (95% identical), zebrafish cacng2a (89% identical), zebrafish cacng2b (85% identical), rabbit CACNG2 (78% identical), Caenorhabditis elegans stg-2 (22% identical). Paralogues in human: CACNG3 (74% identical), CACNG4 (60% identical), CACNG8 (59% identical), CACNG7 (28% identical), CACNG5 (28% identical).
Diseases named in the same sentence as CACNG2 in open-access papers:
CACNG2 is named in the same sentence as 22 diseases in open-access papers, as found by Europe PMC text mining. Sharing a sentence is not in itself a finding about the gene and the disease. The quoted sentences say what the papers report.
epilepsy (8 papers, 2011 to 2024). A brain disorder characterized by episodes of abnormally increased neuronal discharge resulting in transient episodes of sensory or motor neurological dysfunction, or psychic dysfunction. "Mutations in specific genes such as GABRA1, GRIN2A, and CACNG2 have been associated with different types of epilepsy, providing valuable models for understanding how these genetic alterations affect neuronal function and trigger epileptic seizures." (PMID 39452036, 2024). "Ultimately, distinguishing those neurobehavioral consequences that are directly related to Cacng2 loss from those which are secondary to epilepsy in Stargazer mutants remains both a theoretical and practical challenge." (PMID 35896608, 2022). "Many of the selected genes have been found to be associated with neurological diseases, including autism [SHANK2], chronic pain [CACNG2], epilepsy [CHRNB2], Huntington’s disease [GRIN3A], and neurodegenerative diseases [SYBU]." (PMID 32848578, 2020). "Notably, the Cacng2 GA-repeat variation is extensive across different mouse strains and may contribute to other phenotypes, including other epilepsies." (PMID 30478755, 2019). "The FS-DE network has three distinctive VIPs, CACNG2, KCNH3 and GNG3, with relevant roles in epilepsy." (PMID 24278214, 2013).
schizophrenia (4 papers, 2012 to 2024). A major psychotic disorder characterized by abnormalities in the perception or expression of reality. "The association of the polymorphism of CACNG2 and schizophrenia may be related to the calcium influx controlled by the AMPA receptor." (PMID 23555897, 2013). "Between-gene interactions including DAO*DISC1,DAO*NRG1 and DAO*RASD2 and a within-gene interaction for CACNG2 were found among schizophrenia subjects with severe sustained attention deficits, suggesting a modifying effect of impaired neuropsychological functioning." (PMID 23555897, 2013). "Using candidate-gene positional cloning approach we have finely mapped genes vulnerable to schizophrenia in Taiwan, including DISC1 at chromosome 1q42, RASD2 and CACNG2 at chromosome 22q12, and DPYSL2, TRIM35 and PTK2B at chromosome 8p21 (in preparation)." (PMID 23555897, 2013).
bipolar disorder (3 papers, 2007 to 2022). A disorder of the brain that causes unusual shifts in mood, energy, activity levels and the ability to carry out day-to-day tasks. "Among these are rs2284017 (CACNG2) for lithium (as treatment for Bipolar Disorder), rs1801252 (ADRB1) for atenolol (Coronary Artery Disease), and rs429358 (APOC1, APOE) for ritonavir (HIV, HIV infections, Hyperlipidemias)." (PMID 23758991, 2013). "For example, 10 genes among the 16 confirmed genes (Cacng2, Dnajc3, Dusp4, Gpc6, Mbp, Nov, Phf21b, Atxn10, Xbp1, and Zfyve28) have their human orthologs located within a 10 Mb region flanking the linkage markers for bipolar disorder, and thus merit further study." (PMID 18028544, 2007).
breast carcinoma (3 papers, 2021 to 2025). "Although the role of CACNG6 is poorly understood, other members of the TARP family, such as CACNG2, have been linked to chronic pain conditions, including post-mastectomy pain in breast cancer patients and neuropathic pain." (PMID 40577278, 2025). "Similarly, in another cohort, several variants of the CACNG2 gene were found to be associated with CPSP at a nominal level after breast cancer surgery." (PMID 33868360, 2021).
autism (2 papers, 2020 to 2023). Persistent deficits in social interaction and communication and interaction as well as a markedly restricted repertoire of activity and interest as well as repetitive patterns of behavior. "Notably, some constrained genes such as AP2M1 and CACNG2, reported in individuals with cognitive impairment, displayed autism ORs >10 without being included in the lists of autism-associated genes (for example SFARI and SPARK genes)." (PMID 37365347, 2023).
Cognitive impairment (2 papers, 2019 to 2023). Abnormal cognition is characterized by deficits in thinking, reasoning, or remembering. "Among the significantly enriched signaling pathways from KEGG analysis, oxytocin signaling pathway (PATH:04921; Cacng2, Adcy1, Kcnj4, Kcnj9, Adcy8, Pik3cd, Elk1, Adcy4, Camkk2, Cacng7, Nos3, Kcnj2) may play an important role in the sevoflurane-induced cognitive impairment." (PMID 31582589, 2019).
glioblastoma (2 papers, 2022 to 2023). The most malignant astrocytic tumor (WHO grade IV). "According to the signature that included four genes (TMOD2, CACNG2, PLOD3, and TMSB10), glioblastoma patients were divided into high and low risk score groups." (PMID 35788194, 2022). "In glioblastoma, a study constructed a signature by four m7G-related genes (TMOD2, CACNG2, PLOD3, and TMSB10) and could predict the prognosis of glioblastoma patients." (PMID 36732869, 2023).
Intellectual disability (2 papers, 2019 to 2022). "A de novo missense mutation in CACNG2 has been identified in a non-syndromic intellectual disability (ID) patient with moderate severity." (PMID 35256745, 2022).
autism spectrum disorder (1 paper, 2024). A spectrum of developmental disorders that includes autism, and Asperger syndrome. "The CACNG2 gene encoding stargazin is highly constrained and is considered an autism spectrum disorder candidate gene, intolerant to loss-of-function variants [; SFARI database]." (PMID 39895898, 2024).
behavioural disorders (1 paper, 2015). "Finally, many genes associated with neurological development and behavioural disorders were pinpointed (CACNG2, CALN1, ACCN3, EFNB3, DLGAP1 and ATP1B2)." (PMID 26100250, 2015).
Dystonia (1 paper, 2018). An abnormally increased muscular tone that causes fixed abnormal postures. "In fact, virtually all genes associated with dystonia in spontaneous mutants (tottering, stargazer, ophisthotonus, ducky, lethargic, waddles, and wriggle) are involved in Purkinje cell Ca2+ signaling (Canca1a, Cacng2, Itpr1, Cacna2d2, Cacnb4, and Pmca2)." (PMID 29770609, 2018).
glioma (1 paper, 2020). A benign or malignant brain and spinal cord tumor that arises from glial cells (astrocytes, oligodendrocytes, ependymal cells). "Most of them were reported in glioma, CACNG2 JPH3, TUBB6, NRSN1, FAM19A2, NALCN, GNAL have not been reported yet." (PMID 32406502, 2020). "CACNG2, JPH3, TUBB6, NRSN1, FAM19A2, NALCN, GNAL have not been reported in gliomas." (PMID 32406502, 2020). "In addition, there is no report about CACNG2, JPH3, TUBB6 (tubulin β 6 class V), NRSN1, FAM19A2, NALCN, CDH18, GNAL on glioma." (PMID 32406502, 2020). "In addition, CACNG2, JPH3, TUBB6, NRSN1, FAM19A2, NALCN, GNAL were not reported in glioma." (PMID 32406502, 2020).
brain diseases (2 papers, 2015 to 2019). "CACNG2 (TARPγ2, Stargazin) is a multi-functional regulator of excitatory neurotransmission and has been implicated in the pathological processes of several brain diseases." (PMID 30478755, 2019). "The three genes (AP2A2, CACNG2, and RAB3A) in gene sets of at least two brain diseases were significantly enriched 'synaptic transmission' term of Reactome pathway with Benjamini corrected p-value of 0.022." (PMID 26043779, 2015).
CACNG2 also shares sentences with these, for which no sentence is quoted: neurological diseases (2 papers); Ataxia (1); Coronary Artery Disease (1); fragile X syndrome (1); Huntington disease (1); hyperlipidemia (1); ischemic stroke (1); neurodegenerative disease (1); tumor (1).